ADAM8 (ADAM metallopeptidase domain 8)
Diseases named in the same sentence as ADAM8 in open-access papers (continued):
Sharing a sentence is not in itself a finding about the gene and the disease.
glioblastoma (11 papers, 2021 to 2025). The most malignant astrocytic tumor (WHO grade IV). "The metalloprotease-disintegrin ADAM8, which is highly expressed in tumor cells and associated immune cells in glioblastomas, is related to angiogenesis and is associated with a poor clinical prognosis." (PMID 37525217, 2023). "However, since ADAM8 was reported to be highly expressed in tumor-associated immune cells as shown in glioblastoma, the goal of the present study was to analyze the presence of ADAM8 in tumor stroma of PDAC in a cohort of 72 in-house patients." (PMID 33578644, 2021). "Similarly, ADAM8 deficient glioblastoma cells had impaired angiogenesis in in vivo models." (PMID 39329961, 2024). "Recent studies investigating glioblastoma have shown that chemotherapy with temozolomide (TMZ) induces an upregulation of proteases such as ADAM8, ADAM10, and ADAM17, which are likely involved in the cleavage of immunomodulatory molecules like PD-L1." (PMID 40427200, 2025). "ADAM8 was identified as a key mediator of soluble PD-L1 (sPD-L1) generation in glioblastoma cells, with knockout models confirming that sPD-L1 release is largely dependent on ADAM8." (PMID 40427200, 2025). "As shown in glioblastoma cells, ADAM8 mediates angiogenesis by inducing the expression of osteopontin (SPP1) via signal transducer and activator of transcription 3 (STAT3) signaling." (PMID 39412616, 2025). "Indeed, our previous study on glioblastoma revealed that ADAM8 alters the expression profile of the microRNA miR-181a-5p, thereby contributing to tumor aggressiveness." (PMID 39412616, 2025). "ADAM8 can enhance the invasiveness of glioblastoma by activating MAPK signaling." (PMID 39407108, 2024). "The regulation of osteopontin mediates the angiogenic potential of ADAM8 in glioblastoma cells/primary macrophages, so targeting ADAM8 may be a viable approach for modulating angiogenesis in glioblastoma." (PMID 37525217, 2023). "Since the EGFR signaling pathway has been reported to induce CCL2 expression to recruit macrophages in glioblastoma, we propose that ADAM8 could induce TAM recruitment by regulating CCL2 expression via HB-EGF/EGFR." (PMID 36230833, 2022). "Next, we analyzed the expression profiles of ADAM8 and miR-181a-5p in several GBM cell lines, including U87, U251, G112, G28, three primary patient-derived cell lines GBM42, GBM29, GBM98, and three patient-derived Glioblastoma stem-like cell lines (GSCs), 2016/240, 2017/151 and 2017/74." (PMID 35371977, 2022).
colorectal cancer (8 papers, 2014 to 2025). A primary or metastatic malignant neoplasm that affects the colon or rectum. "Furthermore, expression of ADAM8 is associated with cell growth and poor survival of patients with colorectal cancer." (PMID 33314720, 2021). "In this study, we aimed to evaluate the expression of SEMA7A, SEMA4D, ADAM8, and ADAMTS10 in colorectal cancer (CRC) in relation to the mutational landscape of KRAS, NRAS, BRAF, PIK3CA, and AKT genes, microsatellite instability (MSI) status, and clinicopathological features." (PMID 39329961, 2024). "However, no studies have examined ADAM8 association in colorectal cancer (CRC)." (PMID 25098630, 2014).
triple-negative breast carcinoma (7 papers, 2014 to 2024). An invasive breast carcinoma which is negative for expression of estrogen receptor (ER), progesterone receptor (PR), and human epidermal growth factor receptor 2 (HER2). "Via activating the ERK signaling pathway, ADAM8 induced miR-720 expression, which in turn promoted the aggressive phenotype of triple-negative breast cancer cells." (PMID 37508580, 2023). "It was found that ADAM8 promoted the migration and invasion of triple-negative breast cancer cells by activating the ERK signaling cascade." (PMID 36231102, 2022). "ADAM8 (a disintegrin and metalloproteinase 8) protein promotes the invasive and metastatic phenotype of triple-negative breast cancer (TNBC) cells." (PMID 27039296, 2016). "Here, we report that ADAM8 is abundantly expressed in breast tumors and derived metastases compared to normal tissue, especially in triple-negative breast cancers (TNBCs)." (PMID 24375628, 2014).
breast tumors (6 papers, 2014 to 2024). "ADAM8 expression is strongly associated with primary breast tumor formation and metastasis, suggesting that it plays a key role in the development of BC." (PMID 38317965, 2024). "Adam8 is highly expressed in breast tumors, which is associated with an aggressive phenotype and poor patient outcomes." (PMID 37370863, 2023). "They represented that ADAM8 reinforces two steps in brain metastasis process from breast tumor; the first step is “leukocyte mimicry” of cancer cells, which is through stimulating the cleavage of PSGL-1 by ADAM8." (PMID 38317965, 2024). "Here, we report on the preclinical development of a highly specific IHC assay for detection of ADAM8-positive breast tumors." (PMID 37568162, 2023). "In primary breast tumors, Adam8-positive cells are most common in the invasion zone; Adam8 expression is maintained with metastases." (PMID 37370863, 2023). "The result of Romagnoli's study showed that ADAM8 promoted breast tumour cell adhesion onto the endothelium and dissemination via β1‐integrin activation in vivo." (PMID 32954649, 2020). "ADAM8, which is abundantly expressed in aggressive human breast tumors and their metastases, was shown to be essential for tumor growth and dissemination in orthotopic mouse models using knockdown and antibody strategies." (PMID 24375628, 2014). "Immunohistochemical analysis of breast tumors demonstrated that ADAM8 was localized to the cytoplasm and plasma membrane of cancer cells, and was abundantly observed in 34.0% of TNBCs." (PMID 24375628, 2014). "Consistently, ADAM8 protein levels were strikingly higher in primary breast tumor tissue compared to either adjacent normal mammary tissue or fibroadenomas, which are the most common benign tumors of the breast." (PMID 24375628, 2014). "Our findings validate the transmembrane ADAM8 protein as a promising novel target for the treatment of these aggressive breast tumors." (PMID 24375628, 2014). "ADAM8 is abundantly expressed in breast tumors when compared with normal breast tissue." (PMID 38317965, 2024). "Altogether, these findings are consistent with the hypothesis that induction of ADAM8 is required for breast tumors to overcome hypoxic stress." (PMID 24375628, 2014).
hepatocellular carcinoma (6 papers, 2021 to 2023). A malignant tumor that arises from hepatocytes. "Up‐regulation of ADAM8 has been described in hepatocellular carcinoma patients which was associated with poor prognosis." (PMID 33314720, 2021). "This preliminary finding suggested that ADAM8 expression might be associated with malignancy of hepatoma cells." (PMID 33314720, 2021). "Similarly, elevated ADAM8 protein levels in Hepatocellular Carcinomas (HCC) were closely associated with tumor size (P = 0.007) and metastasis (P = 0.003), and higher tumor stage (P = 0.006)." (PMID 37568162, 2023). "Nevertheless, accumulating evidence points in the direction that ADAM8 can induce hepatoma cell proliferation and reduce apoptosis." (PMID 33314720, 2021). "In vitro, ADAM8 expression was upregulated in hepatoma, endothelial, and stellate cell lines by various mediators of steatohepatitis including fatty acid (linoleic-oleic acid), IL-1β, TNF-α, IFN-γ, and TGF-β." (PMID 33814981, 2021). "Hepatoma cells (HepG2 and Hepa1-6) were stimulated with LPS in the presence of metalloproteinase inhibitors with different selectivity and potency for ADAM8." (PMID 33814981, 2021). "Relative ADAM8 mRNA expression was also studied in the established murine hepatoma cell line Hepa1‐6." (PMID 33314720, 2021). "The abundance of PCNA protein in both hepatoma cell lines was clearly down‐regulated in ADAM8 knockdown cells compared to the respective controls." (PMID 33314720, 2021). "This interaction seems to be crucial for the promigratory function of ADAM8 that has been observed in leukocytes and in various cancer cells including hepatoma cells." (PMID 33814981, 2021). "High expression of ADAM8 was noted in the present study in human and murine hepatoma cell lines where ADAM8 was shown up‐regulated on mRNA and protein level compared to healthy murine primary hepatocytes." (PMID 33314720, 2021). "To investigate a mechanistic link between ADAM8 and β1 integrin in hepatoma cells, we examined the expression of β1 integrin and further downstream signalling events in relation to ADAM8." (PMID 33314720, 2021). "Accordingly, we found that ADAM8 protein was significantly stronger expressed in hepatoma cells when compared with healthy primary hepatocytes." (PMID 33314720, 2021). "As focal adhesion kinase (FAK) is a major intracellular signalling mediator of integrins, we also explored the activation of FAK in relation to ADAM8 in hepatoma cell lines." (PMID 33314720, 2021). "Using two hydroxamate-based inhibitors with different selectivity for the protease activity of ADAM8, we obtained initial evidence that ADAM8 activity can contribute to the induced cytokine production in hepatoma cells." (PMID 33814981, 2021). "Our study also revealed a critical function of ADAM8 in hepatoma cell migration as shown by wound healing assays." (PMID 33314720, 2021). "In vitro, stimulation with LPS enhanced ADAM8 expression in murine and human endothelial and hepatoma cell lines as well as in primary murine hepatocytes." (PMID 33814981, 2021). "This band was clearly more prominent when hepatoma cells or endothelial cells were stimulated with LPS confirming the upregulation of mature and active ADAM8 on the protein level." (PMID 33814981, 2021). "In the present study, we demonstrate that β1 integrin expression in hepatocellular carcinoma cells is modulated by ADAM8." (PMID 33314720, 2021). "These two complementary approaches revealed that ADAM8 expression levels correlated positively with proliferation, clonogenicity, migration and matrix invasion and negatively with apoptosis of hepatoma cells." (PMID 33314720, 2021). "Here, we demonstrate that increased ADAM8 expression levels correlate with increased hepatoma cell proliferation." (PMID 33314720, 2021). "In hepatocellular carcinoma, high Adam8 expression is found in the majority of cases." (PMID 37370863, 2023).
hepatocellular carcinoma (continued). "Another related study showed that treatment with recombinant ADAM8 protein caused reduction in proliferation of normal hepatocytes, but not in hepatoma cells." (PMID 33314720, 2021). "We found that ADAM8 was approximately 14‐fold up‐regulated in precancerous cells (n = 4 cell lines, P < .0001) and even 52‐fold up‐regulated in malignant hepatoma cells (n = 4 cell lines, P < .0001), when compared to basal expression in primary hepatocytes of the same genetic background." (PMID 33314720, 2021). "Furthermore, we tested the effect of ADAM8 knockdown on the cytokine release by stimulated hepatoma, endothelial, and stellate cell lines." (PMID 33814981, 2021). "Fatty acids alone induced the expression of ADAM8 at mRNA and protein level in hepatoma cells." (PMID 33814981, 2021). "By contrast, in hepatoma tissue ADAM8 immunoreactivity was broadly distributed and equally intense." (PMID 33314720, 2021). "We and others have recently described the upregulation of ADAM8 in hepatocellular carcinoma." (PMID 33814981, 2021). "Next, we analysed the effect of ADAM8 overexpression on migration and invasion of hepatoma cells." (PMID 33314720, 2021). "In addition, hepatoma cells with high ADAM8 expression were shown to be more resistant to apoptosis." (PMID 33314720, 2021). "However, the role of ADAM8 expression in relation to hepatoma cell proliferation and migration and related signalling mechanisms including the crosstalk of ADAM8 with β1 integrin and FAK remain to be explored in more detail." (PMID 33314720, 2021). "It has been reported that ADAM8 expression is markedly elevated in hepatocellular carcinoma (HCC) tissues in comparison to normal liver tissues." (PMID 35565436, 2022). "In hepatocellular carcinoma (HCC), ADAM8 is highly expressed in murine HCC tissues and hepatoma cell lines, such as murine Hepa1-6 cells and human HepG2 cells." (PMID 36910158, 2023). "In the present study, we demonstrate that ADAM8 is up‐regulated in a murine HCC model in vivo and in immortalized human and murine hepatoma cell lines in vitro." (PMID 33314720, 2021). "To explore the functional role of ADAM8 in control of HCC homeostasis, we knocked down ADAM8 expression in hepatoma cells." (PMID 33314720, 2021). "The release of murine CXCL1 (KC, keratinocyte-derived chemokine) was found attenuated by ADAM8 knockdown in murine hepatoma and endothelial cells but not in stellate cells." (PMID 33814981, 2021). "We here report for hepatoma cells that activation of MAPK/p28 and Src kinase is reduced after ADAM8 silencing and on the other hand the expression of activated Src kinase is increased after ADAM8 overexpression but activation of p28 remained unaffected." (PMID 33314720, 2021). "In conclusion, ADAM8 is overexpressed in HCC and influences hepatoma cell invasion." (PMID 33314720, 2021). "Moreover, the release of human CXCL8 (IL-8) was only attenuated in human hepatoma cells but not in endothelial or stellate cells by ADAM8 knockdown." (PMID 33814981, 2021).
lung carcinoma (6 papers, 2019 to 2024). "ADAM8 is overexpressed in the vast majority of lung cancers and can be a diagnostic marker of lung cancer." (PMID 30669448, 2019). "In this study, we also found that several genes related to the inflammatory response, lymphocyte activation and innate immune response in the mucosa (Hp/Reg3g/Nupr1/Adam8/Cd55/Cfh/Ednrb) were upregulated in mice with EGFRL858R*PTEN-/- induced lung cancer." (PMID 38499532, 2024). "We found four proteins associated with cancer that in observational long time-to-diagnosis analyses, and cis-pQTL and exGS analyses; CD74 and TNFRSF1B were associated with NHL, and ADAM8 and SFTPA2, were associated with risk of leukaemia and lung cancer, respectively." (PMID 38750076, 2024).
colon cancer (5 papers, 2014 to 2024). "Analysis of human colon cancer data from TCGA and GTEx databases identified that ADAM8 is strongly linked to adverse prognosis in patients suffering from colon cancer, but also identified a relationship between ADAM8 and EMT-related biomarkers." (PMID 36910158, 2023). "Analysis of TCGA and GTEx data revealed that ADAM8 was linked to poor overall survival in colon cancer patients." (PMID 32954649, 2020). "In the analysis about public database, it was shown that ADAM8 associated with various EMT biomarkers in colon cancer." (PMID 32954649, 2020). "It was shown that the overall survival of colon cancer patients with high ADAM8 expression was significantly lower than that of patients with low ADAM8 expression." (PMID 32954649, 2020). "Using Transwell invasion assay to assess the effect of ADAM8 on the invasion of tumour cells, knockdown of ADAM8 with siRNA significantly reduced the invasion of colon cancer cells (F = 42.38, P = .0029)." (PMID 32954649, 2020). "The results showed that the level of ADAM8 in colon cancer was significantly related to patients’ AJCC stage, depth of invasion, N stage and distant metastasis (P < .05)." (PMID 32954649, 2020). "The expression of ADAM8 in colon cancer cells was up‐regulated and down‐regulated by transfecting with the expression plasmid and small interfering RNA, respectively." (PMID 32954649, 2020). "Transwell invasion assay, immunohistochemistry, immunocytochemistry, Western blotting and qRT‐PCR were utilized to study the effect of ADAM8 on colon cancer cell's EMT and its related mechanisms." (PMID 32954649, 2020). "The present study elucidated the specific mechanism of ADAM8 promoting colon cancer cell invasion and laid the groundwork for future research of ADAM8 as a promising therapeutic target for colon cancer." (PMID 32954649, 2020). "In a word, these results indicated that ADAM8 was involved in the regulation of EMT processes in colon cancer cells through activating TGF‐β/Smad2/3 signalling pathway." (PMID 32954649, 2020). "The IHC staining scores of ADAM8 in colon cancer tissues were higher than that of adjacent normal mucosa tissues (3.13 ± 0.27 vs 1.17 ± 0.18, respectively; P < .001)." (PMID 32954649, 2020). "In conclusion, our study indicated that ADAM8 was an important biomarker for the prognosis of colon cancer and induced EMT to promote the invasion of colon cancer cells via activating TGF‐β/Smad2/3 signalling pathway." (PMID 32954649, 2020). "Further studies suggested that ADAM8 modulated EMT on colon cancer cells through TGF‐β/Smad2/3 signalling pathway." (PMID 32954649, 2020). "Firstly, qRT‐PCR and Western blotting were utilized to detect the mRNA and protein level of ADAM8 in six common colon cancer cell lines." (PMID 32954649, 2020). "In particular, ADAM8 could promote colon cancer cell invasion by activating the TGF-β/Smad2/3 signaling pathway to induce EMT." (PMID 38025763, 2023). "Besides, ADAM8 is able to trigger EMT to enhance colon cancer cell penetration through activation of the TGF-β/Smad2/3 regulatory signal transduction pathway." (PMID 36910158, 2023). "Thus, ADAM8 induced EMT in colon cancer cells through TGF‐β/Smad2/3 signalling pathway, and integrins were the key mediators between the interaction of ADAM8 and TGF‐β." (PMID 32954649, 2020). "On the contrary, the down‐regulation of ADAM8 in colon cancer cells attenuated these effects above." (PMID 32954649, 2020). "Therefore, combined with the results of Pearson correlation analysis, ADAM8 was an important factor for inducing EMT in colon cancer cells." (PMID 32954649, 2020). "It was shown that ADAM8 reduced the expression of epithelial markers (E‐cadherin) and increased the expression of mesenchymal markers (Vimentin and N‐cadherin), which indicated that ADAM8 could induce EMT in colon cancer cells." (PMID 32954649, 2020).